CD4 (CD4 molecule)
Diseases named in the same sentence as CD4 in open-access papers (continued):
Sharing a sentence is not in itself a finding about the gene and the disease.
tumor (continued). "What’s more, clinical studies indicated that neoantigen-specific CD4+ T cells can be essential for the success of tumor-infiltrating lymphocyte therapy." (PMID 39040850, 2024). "CD4+ T cells increased in all IR-treated tumor tissues, but were higher in IR + CRT3LP and IR + CRT4LP mice than in IR + #DGRLP mice." (PMID 38323311, 2024). "In the group that received a combination treatment of B. longum RAPO with anti-PD-1, researchers observed higher CD8/CD4 T cell ratio levels in the spleen and increased NK cell levels within the tumor." (PMID 38547865, 2024). "A recent study also found that WGP β-glucan can induce up-regulation of CD4+ T cells, down-regulate Treg cells, and improve the immunosuppressive tumor microenvironment." (PMID 39253086, 2024). "In a xenogeneic mouse injected with the MOLM-13 cell line, CD4 CAR-T cells exhibit an 80%–100% of disease control, while CD4 NK-CAR achieved a 98% tumor reduction up to day 9 of treatment." (PMID 38694825, 2024). "In summary, after two vaccinations, p15E-3C mimotope vaccinated mice dependent on CD8+ T cells instead of CD4+ T cells to inhibit MC38 tumor growth." (PMID 38506662, 2024). "The only significant difference was observed for expression of CTLA-4 on CD4 cells in relation to the size of the tumour." (PMID 39474426, 2024). "The cancer-immunity cycle underscores dendritic cells' (DC) pivotal role in priming CD4+ and CD8+ T-cells through presentation of tumor-associated antigens (TAAs) in tumor-draining lymph nodes (TDLN)." (PMID 38954010, 2024). "The interaction between depleted or dysfunctional CD8 + and CD4 + tumor-infiltrating lymphocytes (TILs) and the B-cell recruiting ligand CXCL13 leads to the formation of tertiary lymphoid structures (TLS)." (PMID 39068459, 2024). "We observed increased staining of T cells (CD3+) and CD4+ in CR705Parp7KO compared with CR705Cas9 tumours." (PMID 39867896, 2024). "A small proportion of CD4+ T cells were DP, and they were more dominant in central and peripheral tissues than in non-tumor tissues." (PMID 38335302, 2024). "While such an approach did lead to B-cell depletion and signs of cytokine release syndrome (CRS), the utilization of CD4 lentiviral vectors led to the production of anti-CD-19 CD4+ CAR T cells that led to more efficient tumor cell killing activity." (PMID 39835140, 2024). "RANTES, which is associated with recruitment of cytotoxic, IFNγ-producing CD4 and CD8 T cells that interact with anti-tumor macrophages, was profoundly up-regulated, and pro-inflammatory (M1) cytokines IL-12 and IFNγ increased." (PMID 38458648, 2024). "Here, we reported that the natural product rocaglamide (RocA) increased tumor-infiltrating T cells and promoted Th17 differentiation of CD4+ TILs." (PMID 38833034, 2024). "Regulatory T (Treg) cells, a specific subgroup of CD4+ T cells, contribute to tumor immune tolerance by inhibiting the proliferation and promotion of immune cells and secreting anti-inflammatory chemicals." (PMID 39678492, 2024). "While Foxp3+CD4+ T cells, also known as Tregs, distribution in tumour tissue alone has been extensively studied, the results remain controversial." (PMID 39409156, 2024). "Compared to the NDV-GP-treated group with no T cell transfer, single adoptive transfer of memory CD8+ or CD4+ T cells resulted in limited tumor retardation in mice administered NDV-GP." (PMID 38609488, 2024). "We further reveal how the presence of Her2+ tumor cells results in a suppressive phenotype for CD4+ cells, and that depletion of CD4+ cells leads to elimination of influenza virus infection expanded DCC, dependent on CD8+ cells." (PMID 38645169, 2024). "To explain the potential reasons for the sensitization to ICI therapy with cuproptosis treatment, we analyzed tumor tissues by serial sections and evaluated the infiltration of CD4+ and CD8+ T cells among different treatment groups using immunohistochemistry." (PMID 38931345, 2024).
tumor (continued). "After HN-1 treatment, the proportion of anti-tumor immune cells (DCs and CD4+ and CD8+ T cells) increased, but the percentage of immunosuppressive Treg cells decreased." (PMID 38970078, 2024). "CD4+ T cell depletion also resulted in larger tumour sizes in poly(I:C)-treated sites compared to CD8+ T cell depletion." (PMID 38472944, 2024). "While certain immune cell types such as neutrophils, macrophages, and CD4+ regulatory T cells have been observed to facilitate tumor growth, others like CD8+ cytotoxic T cells, natural killer cells, and gamma-delta T cells actively engage in tumor eradication." (PMID 38612457, 2024). "These markers are important for presenting antigens to CD4 + T cells and play crucial roles in anti-tumor immunity." (PMID 38951896, 2024). "We conducted IHC staining of CCL11, CD4, and Foxp3 proteins in serial sections of the same tumor tissues from BRCA patients." (PMID 38305920, 2024). "Decreased miR-29b levels in CTCL patients’ CD4 (+) T cells resulted in BRD4 overexpression, which was associated with elevated levels of the interleukin-15 (IL-15) receptor complex and tumor-related genes (including RBPJ and NOTCH1)." (PMID 39256366, 2024). "It is well-known that effector CD8 cells need the help of CD4 cells in vivo in immune responses to infectious diseases as well as in TCR-driven anti-tumor immune responses." (PMID 38789421, 2024). "Nonetheless, numerous studies have shown that EVs derived from tumor cells are capable of migrating tumor associated antigens to the host cells, thus stimulating anti-tumor immunity by activating CD8(+) and CD4(+) T cells." (PMID 39281673, 2024). "Immunization significantly impaired tumor growth and prolonged survival in transplantable tumor models, with CD4+ T cells and B cells identified as key mediators of the anti-tumor response." (PMID 39081320, 2024). "The results showed that mice undergoing two freeze/thaw cycles on the left-sided tumor had the longest survival, the slowest growth rate of the right-sided tumor, and a higher proportion of CD4+ and CD8+ tumor-infiltrating lymphocytes(TILs)." (PMID 38384806, 2024). "Among them, the proportions of naïve B cells, CD8 T cells, CD4 naïve T cells, and CD4 memory-activated T cells were higher in the “hot” tumor (P < 0.05)." (PMID 39007147, 2024). "Tumor growth control mediated by CD4+ GMTC has the same amplitude but is less durable than the one mediated by the total GMTC." (PMID 38545119, 2024). "We further went on to identify that Zn supplementation during tumor development alters mainly CD4 T-cell subtypes by suppressing the T helper 1 (Th1) cell population and enhancing the Foxp3+ Treg cell population." (PMID 39247196, 2024). "So we collected common tumor exposure factors and performed multiple Mendelian randomization (MR) analysis on NB, and ultimately determined that the increase in Resting CD4 regulatory T cell was positively correlated with the occurrence and development of NB." (PMID 40625890, 2024). "To this end, we isolated splenocytes from naive C57BL/6 mice or mice injected with Mgat5-WT or Mgat5-KO tumor cells for T cell receptor Vβ repertoire analysis of both CD4+ and CD8+ T cells." (PMID 38912584, 2024). "Although CD4 + T cells can recognize the epitope of tumor cell MDM2 and directly eliminate tumor cells, immune tolerance still develops." (PMID 38281981, 2024). "Most studies have observed a marked increase in CD4+ T cell infiltration at the periphery of CCA compared to the central region of the tumor." (PMID 39845973, 2024). "In the TME, CD8+ T lymphocytes, CD4+ T lymphocytes, and NKs are activated to block tumor propagation and inhibit immune escape." (PMID 39845973, 2024). "This study demonstrated that tumor resection partially restores circulating CD4+ Treg cell levels in CCA and HCC patients." (PMID 39408071, 2024). "MPO deficiency significantly reduced CD11b+Ly6G+ myeloid cells, macrophages and exhausted CD4+PD1+CTLA4+ T cells within the tumor microenvironment." (PMID 38367056, 2024).
tumor (continued). "When combining the results of DNA and RNA sequencing for tumor cells of cancer patients, neoantigens that potentially stimulate the immune response of either CD4+ or CD8+ T cells can be identified." (PMID 39327585, 2024). "Tumor tissues from these mice showed increased mature dendritic, CD4+ T, and CD8+ T cells and pro-inflammatory cytokines (IFNγ and TNFα) and decreased regulatory T cells, and the expression of tumor cell proliferation markers (Ki67 and CD31) was downregulated." (PMID 38323311, 2024). "CD4+ and CD8+ T cells have a crucial role in tumor immunosurveillance via the recognition of tumor-associated antigens (TAAs), which results in the secretion of various cytokines and chemokines and then a powerful cytotoxic response against cancer cells." (PMID 39430751, 2024). "Analysis of the graft tumor microenvironment by flow cytometry showed an increase in CD8+ and CD4+ T-cell infiltration detected in the B16F10 tumor graft after Mi-2β silencing, which was strongly augmented by anti-PD-1 treatment." (PMID 38461299, 2024). "Our observations from the co-culture of UPP1-overexpressing tumor cells with CD4 + T cells highlighted that UPP1 upregulation in tumor cells significantly drove the differentiation of CD4 + T cells into CD25 + FOXP3+Tregs." (PMID 38331898, 2024). "In the current study, we demonstrate that the loss of infiltrating Tregs not only enhanced early-stage CD8+ TIL effector activity but also inhibited TOX induction, preventing the CD4+ T cell transition into functional exhaustion during tumor progression." (PMID 38787791, 2024). "The role of CD4+ T cells in promoting the generation of effector CD8+ T cells for tumor immunity has garnered significant attention, as evidenced by extensive research." (PMID 38426090, 2024). "In this groundbreaking study, the authors have successfully demonstrated that the utilization of AOA results in a remarkable reduction in tumor growth rate and an impressive enhancement in the infiltration of CD4 + and CD8 + T cells." (PMID 38459595, 2024). "NLRP3 inflammasome activation can also promote intestinal epithelial cells to secrete IL-18, exerting an anti-tumor effect on immune cells such as CD4+ T cells (in AOM-induced colorectal cancer)." (PMID 38887519, 2024). "vi Tumor-infiltrating lymphocytes (TILs)–TILs–T (CD4+ and CD8+) and B lymphocytes infiltrate the tumor mass and recognize and destroy abnormal cells." (PMID 39201585, 2024). "Recent clinical evidence supports the importance of CD4+ T cells in generating successful anti-tumor immunity." (PMID 39510069, 2024). "Combining Mw with these therapies is associated with an increase in absolute number of tumor-infiltrating lymphocytes (TIL) and an increased frequency of CD4+ and CD8+ T cells with a decrease in FoxP3 and PD-1 expressing TIL." (PMID 39534596, 2024). "These circulating CD4(+) T cells contribute to the activation of peripheral blood CD8(+) T cells within the tumor microenvironment through the production of IL-21, thereby enhancing the cytotoxic function of infiltrating CD8(+) T cells." (PMID 38395827, 2024). "Subsequently, the term “agranular CD4+CD56+ hematocutaneous neoplasm/tumor” was coined, reflecting the immunophenotype and skin lesion propensity." (PMID 39590155, 2024). "Immune cells like CD4+ T cells and neutrophils were also reported to be dual functional in tumor immunity." (PMID 39712017, 2024). "The low HIGD1B group showed higher infiltration of T cells CD4 memory activated B with anti-tumor effects, while the high HIGD1B group had more macrophage M2 infiltration." (PMID 39108265, 2024). "In contrast, Cluster3 displayed higher levels of CD4 + T cells, CD8 + T cells, NK cells, B cells, cancer-associated fibroblasts, and endothelial cells, suggesting an abundance of tumor-killing effector cells." (PMID 39160604, 2024). "The level of granzyme B + CD4 + T cells was increased in both single PAK KO tumours, with a further significant increase in PAK1&4 double KO." (PMID 38797819, 2024).
tumor (continued). "Co-culture of 1B3-transfected tumor cells and immature DC led to DC maturation and these mature DC were able to stimulate production of type 1 cytokines by CD4+ and CD8+ T cells." (PMID 39007281, 2024). "As the major cytotoxic cells in the tumor microenvironment, the fractions of CD8+ T cells were negatively associated with those of resting memory CD4+ T cells, M0 macrophages and activated dendritic cells." (PMID 38017652, 2024). "Lastly, HLA-II neoantigens were not assessed in our study and should be investigated in the future considering the critical role of CD4 T cells in anti-tumor responses." (PMID 38331912, 2024). "As the main force in the antitumor immunity of NB, T lymphocytes (CD8+ T cells or resting memory CD4+ T cells) can significantly inhibit tumor development and improve prognosis, as expected." (PMID 39575432, 2024). "Investigating tumor-infiltrating lymphocytes is essential to developing immunotherapies and the prediction of their clinical responses with regard to the link between CD4+ T lymphocytes phenotype and malignancy." (PMID 38690280, 2024). "PD-1 expression on the tumor-infiltrated CD4 T cells, CD8 T cells, and γδT cells were suppressed in the DT-treated groups with or without Zn supplementation." (PMID 39247196, 2024). "Unsupervised analysis identified a subset of effector CD8+ T cells and a subset of memory CD4+ T cells, which were increased in tumor samples obtained after treatment in responders compared to non-responders." (PMID 39273452, 2024). "The association between SCD or FADS2 expression and tumor-infiltrating immune cells (B cells, CD8+ T cells, CD4+ T cells, macrophages, neutrophils, and dendritic cells) in BRCA was determined using the TIMER tool." (PMID 38905386, 2024). "CTLs can specifically recognize tumour cells via the chemokines secreted by DCs and the signaling pathway of CD4+ T cells, and they secrete perforin and granzyme B to induce apoptosis in target cells." (PMID 38475858, 2024). "In our previous study, we found that PD-L1 expression evaluated by TPS, IC, and CPS was significantly associated with the CD4+ T cells, Foxp3+CD4+ T cells, CD8+ T cells and M2 macrophage infiltration in the whole tumour tissue." (PMID 39409156, 2024). "This improvement was linked to an enhanced activation of total T cells, CD4+ helper T cells, and CD8+ cytotoxic T cells in both the draining lymph node and tumor." (PMID 39199612, 2024). "The anti-tumour CD4+ T cells in colorectal cancer patients receiving oxaliplatin chemotherapy response can still be observed in some patients three months after treatment." (PMID 38475858, 2024). "The proportion and distribution of tumor-infiltrating CD4+ T lymphocytes in CCA subtypes exhibited significant disparities." (PMID 39845973, 2024). "That facilitated the migration of α4β7+ CD4+ Treg17 cells to the tumor, mediating immune evasion and compromising the efficacy of immunotherapy." (PMID 38566102, 2024). "For example, IL-2, IL-12, and IL-15 are able to drive the proliferation of effector CD8+ and CD4+ T cells in peripheral lymphoid tissues and the tumor microenvironment, thus amplifying the overall CTL response and antitumor efficacy." (PMID 39617785, 2024). "They found that PE promoted the expression of MHC II and co-stimulatory molecules CD86 and CD80 on tumor-associated dendritic cell (TADCs), induced the production of IL-12 by TADCs, and enhanced the proliferation of both CD8+ T and CD4+ T cells." (PMID 39364399, 2024). "Although angiogenin has been shown to promote tumor growth and angiogenesis, its upregulation in the alloreactive immune response has been shown to inhibit apoptosis of CD4+ T cells." (PMID 38245670, 2024).
tumor (continued). "Mechanistically, immunotherapy stimulates the production of IL-5 and IL-33 by CD4+ T cells, which induces the production of eosinophils in the bone marrow, increased systemic eosinophil circulation, and accumulation in the tumor site." (PMID 39496729, 2024). "This implies a direct interaction between tumor cells and CD4+ T-cells operating independently of cytokine-mediated pathways." (PMID 39123357, 2024). "This study aimed to explore the relationship between these novel subtypes and the tumor immune microenvironment (TIME), particularly CD8+ and CD4+ tumor-infiltrating lymphocytes (TILs)." (PMID 39682568, 2024). "Neutrophils are especially important for cleaning and repairing the ablated site, while the newly recruited CD4+ naïve T cells can be activated by antigen presenting cells and aid in the elimination of tumor cells." (PMID 39703517, 2024). "Adoptive cell transfer of neoantigen-reactive CD4+ T cells resulted in tumor regression in a patient with epithelial tumor." (PMID 39569190, 2024). "Profoundly, we found that depletion of either CD4+ or CD8+ T cells resulted in impaired of tumor suppressive effects of TAM CD276 cKO on BLCA." (PMID 38561369, 2024). "Firstly, the infiltration of T cells (CD3, CD4, CD8, GZMB), tumor-associated macrophages (TAMs, CD11b), B cells (CD24) and NK cells (CD56) within the tumor was assessed by immunohistochemical (IHC) staining." (PMID 38622609, 2024). "Mucinous tumors, which had immune infiltration frequently found in focal clusters, had significantly higher levels of CD8 and CD4 and low level of immune suppressive markers and checkpoints in the immune AOIs, and tumor AOIs with higher expression of VISTA." (PMID 39026018, 2024). "The double combination therapy resulted in large proportions of GzmB-positive CD8 and CD4 T cells in both tumor models." (PMID 38167722, 2024). "GZMB, which can inhibit aberrant IL‐17 production in CD4+ T cells, thereby impeding angiogenesis and subsequent tumor development, was upregulated in CD4+ Th17 cells in HB group." (PMID 39135526, 2024). "CD4+ T‐cell differentiation generates regulatory T cells (Tregs), which are immunosuppressive lymphocytes recruited to the milieu to facilitate tumour cell escape from immune surveillance." (PMID 38468489, 2024). "Recently, more and more research illustrated the importance of inducing CD4+ T helper type (Th)-1 dominant immunity for the success of tumor immunotherapy." (PMID 38827732, 2024). "Specifically, CD4 memory-activated T cells, naïve B cells, and plasma cells were found to be substantially elevated in tumor samples compared to normal samples." (PMID 38338834, 2024). "In the early stages, IL-6 and IL-17 work to elevate a pro-tumor effect by stabilizing the CD4+ Th17 phenotype." (PMID 38279220, 2024). "The tumor-infiltrating CD4+T cells isolated from the HS diet cohort of the Py230-C57Bl/6J murine model demonstrated that there was reduced cytotoxicity against tumor cells (E:T ratio 20:1) from passage 1 (45.7 ± 6.6%) to passage 4 (11.3 ± 2.7%; p < 0.05)." (PMID 38891044, 2024). "We confirmed that similar to killing of NALM6 tumor cells, both CD8 and CD4 CAR T cells were capable of killing these tumor targets at the single-cell level." (PMID 38307835, 2024). "Tregs are a highly immunosuppressive subset of CD4+ T cells and as a gatekeeper for immunological homeostasis, suppressing effective anti-tumor immunity through different mechanisms." (PMID 38357546, 2024). "Meanwhile, cytotoxic CD4+ T cells capable of lysing tumor cells require MHC-II neoantigen presentation on tumor cells." (PMID 39569190, 2024). "Among them, CD4_C3_CXCL13 T cells emerged as the most extensive communicative with HPV+ tumor cells, especially through CD74-COPA, CD74-MIF and CD2-CD58, which play a critical role in MHC-II antigen presentation and T cell activation." (PMID 39105803, 2024).